INS (insulin)
Diseases named in the same sentence as INS in open-access papers (continued):
Sharing a sentence is not in itself a finding about the gene and the disease.
insulinoma (continued). "Laboratory results from a venous glucose level of 46 mg/dL indicated a notable rise in C peptide and insulin levels, alongside beta hydroxybutyrate suppression, all of which fulfilled the diagnostic criteria for insulinoma." (PMID 38074057, 2023). "Excessive insulin secretion by insulinoma causes hyperinsulinemic hypoglycemia, which leads to neuroglycopenic, autonomic, adrenergic, and cholinergic symptoms." (PMID 37286698, 2023). "As witnessed in RIP-Tag mice, altered insulin production causes rapid mortality, thus, homozygous inactivating models avoid insulinomas." (PMID 37568572, 2023). "Historically, several other diagnostic tests have been used in the diagnostic work-ups of canine insulinoma patients, including the amended insulin-to-glucose ratio, the intravenous glucose tolerance test and the glucagon tolerance test." (PMID 36288153, 2022). "Insulinoma is characterized by a loss of normal pancreas architecture due to localized hyperplasia of insulin-producing cells." (PMID 34497584, 2021). "This loss of insulin secretion function that occurs with subsequent cell divisions limits the clinical usefulness of such insulinoma cell lines in the development of a biological pancreas for transplantation." (PMID 34940547, 2021). "Insulinoma is a rare pancreatic neuroendocrine neoplasm (PanNEN) and causes hypoglycemia owing to insulin oversecretion." (PMID 34294854, 2021). "FAC was previously used to induce the excess intracellular iron and caused increasing of ROS affected insulin secretion in Rat insulinoma pancreatic β-cells (RINm5F) as a model of pancreatic iron overload in β-thalassemia patients." (PMID 32587797, 2020). "SIRT4 deficiency activates GDH, stimulating amino acid-mediated insulin secretion in insulinoma cells." (PMID 33117804, 2020). "In other HH disorders, e.g. insulinoma, supporting diagnostic evidence is the insulin-glucose ratio, or the amended insulin-glucose ratio, where 1.7 mmol/L is subtracted from the glucose value." (PMID 33679602, 2020). "Insulinomas are rare, benign beta cell tumours which overproduce insulin and have been associated to epigenetic alterations." (PMID 33060578, 2020). "Against this background, the present study was performed to delineate the mechanism underlying the induction and regulation of insulin gene transcription in insulinoma cells." (PMID 30790128, 2019). "If insulinoma is excluded, another possible cause of endogenous insulin overproduction is nesidioblastosis - hypertrophy/hyperplasia of pancreatic β-cells." (PMID 31777577, 2019). "Simultaneous occurrence of blood glucose < 3.5 mmol/L (reference interval: 4.2–5.8 mmol/L) and plasma insulin > 10 mIU/L (reference interval: 1.4–24.5 mIU/L) were considered diagnostic for insulinoma." (PMID 29806550, 2018). "In a model for the human islet cancer insulinoma, β cells can be driven to proliferate by c-Myc overexpression and this is usually accompanied by loss of insulin expression." (PMID 28457793, 2017). "C-Myc upregulation in adult islets in a mouse model of insulinoma has a potent pro-proliferative effect and also results in loss of insulin expression and a failure to maintain blood glucose homeostasis." (PMID 28457793, 2017). "In conclusion, our data suggests that insulinoma cell lines show a clear requirement for glucose driven mitochondrial OXPHOS linked to insulin secretion." (PMID 31754635, 2017). "The appropriate diagnostic steps for a biochemical diagnosis of insulinoma include determination of circulating levels of insulin and C-peptide, and plasma insulin/glucose ratio." (PMID 25816027, 2015). "This test can also be associated with a mathematically calculated value of insulin/glycemia ratio which in the presence of insulinoma must be superior to 0.3." (PMID 24213321, 2012).
insulinoma (continued). "The present data indicate that a reduction in the expression level of ZnT8 is associated with a marked decrease in intracellular insulin content in cultured rat insulinoma cells, and a reduction in the glucose-stimulated secretion of insulin." (PMID 19479076, 2009). "Blood tests showed a decreased value of glycemia (30mg/dl) associated with increased insulin level (16μU/ml) and an increased glycemia/insulinemia ratio of 1.87 supporting the diagnosis of insulinoma." (PMID 20108468, 2008). "In addition to insulin therapy, tumors such as insulinomas of pancreatic origin and extrapancreatic tumors causing paraneoplastic syndromes should also be considered." (PMID 37823058, 2023). "Thus, a solid-nested pattern with amyloid is usually associated with the expression of insulin and is found in insulinomas." (PMID 34647171, 2022). "We selected the murine insulinoma INS-1E cells for assessing the consequences of NAF-1 deficiency on pancreatic β-cells of WFS-T2 primarily on the basis that these cells respond to glucose stimuli by secreting insulin." (PMID 34439408, 2021). "In the same study, the authors tested the effect of a 4-week treatment with the Hh signaling inhibitor GDC-0449 (SMO inhibitor) on 8-month-old Men1-mutated mice with insulinomas, showing a reduction of proliferation of beta cells of approximately 60% and a reduction of circulating levels of insulin." (PMID 33919851, 2021). "Variants in other autoantigens, such as those targeting pre-proinsulin, β-cell specific zinc transporter 8, insulinoma-associated antigen 2, the insulin gene, the cytotoxic T-lymphocyte–associated protein-4, and the interleukin-2 receptor are also known to contribute to the susceptibility of T1DM." (PMID 33585535, 2020). "Association of pericentrin with insulin granules from mouse insulinoma cells was also observed by immunofluorescence of purified granules and by Western analyses of post-nuclear supernatant fractions (excluding DNA and centrosomes) derived from iodixinol density gradients." (PMID 20676397, 2010). "Unregulated insulin secretion by the insulinoma could, in theory, result from any mutation of either SUR 1 or Kir6.2 that promotes KATP channel closure or impairs normal metabolic regulation." (PMID 16266437, 2005). "Therefore, there has been an urgent demand for non-invasive, highly sensitive diagnostic methods for insulinoma, also reflecting the tumor’s insulin secretion function and serving as an alternative option to currently employed diagnostic interventions with significant patient burden." (PMID 40405975, 2025). "Moreover, serum insulin concentration is also a qualitative diagnostic method for insulinoma." (PMID 32506749, 2020). "In addition, insulinomas secrete insulin, causing temporary fluctuations in blood sugar levels." (PMID 32009878, 2019). "In addition, we found that both rapidly-dividing insulinoma cells, as well as quiescent primary pancreatic islets, exhibited loss of intracellular insulin with pericentrin depletion, suggesting this phenotype was not secondary to pericentrin-dependent effects on cell cycle progression." (PMID 20676397, 2010). "To assess the functional impact of these metabolites, we utilized the INS-1 832/3 insulinoma cell line, evaluating insulin sensitivity through glucose-stimulated insulin secretion and ERK1/2 activation." (PMID 41599892, 2026). "The insulinoma in Patient 1 contained a considerably lower proportion of insulin-expressing cells than the primary tumour in Patient 2 (a total of 5.5% versus 59.5%, Fisher's Exact p < 2.2e- 16)." (PMID 40438247, 2025). "The maximum hepatic venous insulin concentration (mHVI) and relative fold hepatic venous insulin concentration (rHVI) were significantly higher in an insulinoma compared to nesidioblastosis." (PMID 40395710, 2025).
insulinoma (continued). "It is important to understand the biology of metastasis in canine insulinoma because the main reason for the poor long-term prognosis is the development of functional insulin-secreting metastatic lesions after surgery." (PMID 40438247, 2025). "A combination of results—glycemia <2.5 mmol/L, insulin levels >20.8 pmol/L, and C-peptide levels >0.2 nmol/L—is highly indicative of the presence of an insulinoma." (PMID 40565772, 2025). "Insulinomas, NETs that produce insulin and are predominantly found in the pancreas, frequently exhibit mutations in the transcription factor YY1, which is absent in nonfunctioning pancreatic NETs." (PMID 40026252, 2025). "Even if there are two or more pancreatic arterial distributions, the degree of insulin elevation can aid in differentiating an insulinoma from nesidioblastosis, since insulinomas tend to release higher amounts of insulin into the circulation." (PMID 40395710, 2025). "GPR162 is also present in human and murine pancreatic islets, and has been shown to regulate cocaine-amphetamine-regulated transcript (CART)-induced insulin secretion in a rat insulinoma cell line INS-1 832/13." (PMID 40544420, 2025). "A study conducted in 2021 demonstrated that silencing of Cpne3 in a rat insulinoma cell line suppresses glucose-stimulated insulin secretion." (PMID 41465472, 2025). "In the pancreatic β-cells, cAMP is rapidly degraded by the cyclic 3′, 5′-nucleotide phosphodiesterase 3B (PDE3B), and overexpression of PDE3B in rodent islets or rat insulinoma INS-1 cells decreases insulin secretion in response to glucose and GLP-1." (PMID 40024571, 2025). "Differential diagnoses should include insulinoma, extrapancreatic neoplasms, use of sulfonamides, and exogenous insulin administration." (PMID 39968421, 2025). "Specifically, the membrane progesterone receptor component PGRMC1 has been reported to cross-talk with and enhance GLP-1-induced insulin secretion in a rat insulinoma cell line." (PMID 40002193, 2025). "Background/Objectives: Insulinomas are rare insulin-secreting pancreatic neuroendocrine tumours (pNETs)." (PMID 41375058, 2025). "Emphasizing its role in insulin secretion, inhibition of PKA in rat insulinoma RIN 1046-38 cells attenuates insulin secretion induced by GLP-1 or other cAMP elevating agents." (PMID 40024571, 2025). "Most patients with insulinoma present with the classic Whipple’s triad due to excessive secretion of insulin or proinsulin by tumor cells." (PMID 41488138, 2025). "In this case, blood glucose was at hypoglycemic levels just 5 h after the last meal—an early onset that underscores the unregulated insulin secretion from the tumor and supports the diagnosis of insulinoma." (PMID 40124204, 2025). "Among them, insulinoma is the most common functional PNEN that is characterized by excessive amounts of insulin secreted." (PMID 39897806, 2025). "Serum LEAP2 levels were significantly higher in patients with insulinoma than in controls (P = 0.028) and positively correlated with serum insulin levels (r = 0.408, P < 0.001) while negatively correlated with ghrelin levels (r = −0.551, P < 0.01)." (PMID 41488138, 2025). "Among the non-insulinoma PanNETs, immunohistochemical insulin or proinsulin positive cases were categorized as Inspos, and both negative cases as Insneg." (PMID 40281248, 2025). "In PanNET cases other than insulinoma, insulin- or proinsulin-IRS-positive cases were categorized as Inspos, both negative cases as Insneg, referring to a previous study." (PMID 40281248, 2025). "Staining of the pancreatic specimen with an anti-insulin antibody confirmed the presence of insulinoma." (PMID 41199767, 2025). "Subsequent multimodal imaging evaluation, including PET-CT, octreotide scintigraphy, and contrast-enhanced pancreatic MRI, effectively excluded insulinoma or other insulin-secreting neoplasms, ultimately confirming the diagnosis of IAS." (PMID 41239648, 2025).
insulinoma (continued). "Fasting serum insulin concentrations were significantly higher in 74 patients with insulinoma than in 28 controls (median 18.9 μIU/mL, range 2.8-300 μIU/mL vs. median 3.9 μIU/mL, range 2.2-10.7 μIU/mL, P <0.0001)." (PMID 41488138, 2025). "GLP-1 stimulation of insulin production was first shown in rat insulinoma RIN1046-38 cells and later confirmed by other studies." (PMID 40024571, 2025). "Serum LEAP2, insulin, and ghrelin levels were measured by ELISA in patients with insulinoma and in age-, sex-, and BMI-matched controls." (PMID 41488138, 2025). "Biochemical testing and arterial catheterization revealed elevated insulin levels, leading to laparoscopic distal pancreatectomy, where an insulinoma was confirmed." (PMID 40981133, 2025). "Insulinomas are the most common functioning PNETs, characterized by inappropriate and autonomous insulin secretion, often resulting in symptoms of neuroglycopenia such as confusion, seizure, and altered mentation." (PMID 40757084, 2025). "If the CaSR was essential in insulin secretion it would be expected that its expression would be maintained in insulinomas." (PMID 39579056, 2025). "Global knockout of Ptprn led to impaired glucose-mediated insulin secretion, whereas overexpression of Ptprn in an insulinoma cell line led to increased insulin secretion." (PMID 39926347, 2025). "Insulinomas are rare pancreatic neuroendocrine tumours that systemically secrete insulin, resulting in severe hypoglycaemia." (PMID 41375058, 2025). "The pivotal role of AdSS in coordinating purine and carbohydrate metabolism was supported by findings from a metabolite screening of endogenous factors that mediate glucose-induced insulin secretion in the rat insulinoma cell line 832/13." (PMID 40331943, 2025). "Firstly, all three insulinoma samples contained two distinct populations of insulin-expressing cancer cells, with very different transcriptomic profiles." (PMID 40438247, 2025). "In both species, neoplastic insulinoma β-cells secrete insulin in an uncontrolled fashion, leading to hyperinsulinemia-induced hypoglycemia." (PMID 39828734, 2025). "In fact, studies have shown a 30% increase in glucose-stimulated insulin secretion upon overexpression of cNADK, and cNADK knockdown induces a significant inhibition of the secretion in a pancreatic insulinoma cell line." (PMID 38988322, 2024). "Insulinoma 2 showed both insulin and glucagon staining in the insulinoma tissue and INS-DRiP colocalized with insulin+ cells and glucagon+ cells, and triple positive cells." (PMID 38596681, 2024). "Clinically, insulinomas manifest through hypoglycemic episodes resulting from unregulated insulin secretion." (PMID 39677258, 2024). "Selective arterial calcium stimulation test (SACST) is an invasive procedure that involves injecting calcium gluconate into the arteries, supplying the pancreas with insulin to stimulate insulin release from potential insulinomas." (PMID 39555226, 2024). "Insulinoma is the most common functional neuroendocrine tumor of the pancreas, and it secretes insulin, leading to hypoglycemia." (PMID 39070407, 2024). "During ASVS insulin level elevation was found to be significantly higher in insulinomas than in nesidioblastosis." (PMID 39497809, 2024). "SphK1 knockdown in rat insulinoma INS-1 832/13 cells reduced insulin synthesis and secretion, whereas SphK1 overexpression restored them." (PMID 38256005, 2024). "The uncontrolled insulin secretion from insulinoma persistently drives glucose uptake into the tissues and suppresses hepatic gluconeogenesis." (PMID 39723310, 2024). "The presence of high insulin and high C-peptide levels point toward insulinoma and insulinogenic drugs while laboratory findings in NICTH often include decreased levels of insulin, C-peptide, growth hormone, and IGF as well as increased IGF-II/IGF-I ratio." (PMID 39651031, 2024).
insulinoma (continued). "In the INS-1 832/3 rat insulinoma cell line, the cells were stimulated to release insulin by performing low- and high-glucose concentration incubation (2.5 mM and 15 mM, respectively)." (PMID 39337311, 2024). "Here, we use direct current insulator-based dielectrophoresis (DC-iDEP) as an unbiased separation method and demonstrate its capability by identifying distinct distribution patterns of insulin vesicles from INS-1E insulinoma cells." (PMID 39190030, 2024). "Consistent with Pdx1-CreER expression in pancreatic β-cells, the MAP model developed PanNET insulinomas (see insulin expression." (PMID 38609433, 2024). "The studies demonstrated that the identified GOF variants (p.Pro330Ser; p.Glu357Lys) led to hyper‐inhibition of ISL1 and consequently to a decrease in insulin gene expression in a rat insulinoma cell line." (PMID 38404237, 2024). "In insulinoma 1, INS-DRiP colocalized with insulin in insulinoma tissue and beta cells of a neighboring islet, as shown on the islet–insulinoma interface." (PMID 38596681, 2024). "Here, we demonstrate the power of DC-iDEP in organelle separation, by using it to investigate subtle differences in the subpopulations of insulin vesicles upon differential stimulation in the INS-1E insulinoma model of the pancreatic β-cells." (PMID 39190030, 2024). "In conclusion, this study demonstrates that nanomolar concentrations of serotonin (10–100 nM) play a regulatory role in insulin synthesis and secretion in rat insulinoma INS-1E cells." (PMID 38999937, 2024). "Diagnosis of insulinoma is based on clinical picture and consistent biochemical tests, and low glucose level (2.5 mmol/l) accompanied by high insulin level (more than 6 μU/mL)." (PMID 39057179, 2024). "Recent data showed that hypercalcemia in patients with insulinoma in MEN1 influences the insulin pattern of secretion." (PMID 38928056, 2024). "During therapy, patient showed early clinical and imaging response for insulinoma leading to unmasking of poor glycemic control necessitating requirement of insulin administration for DM." (PMID 39677350, 2024). "The intracellular mTOR pathway is involved in β-cell growth and altered insulin secretion in patients with insulinoma, ketone body synthesis, and insulin action." (PMID 39153498, 2024). "Here, we investigated how exogenous nanomolar serotonin concentrations regulate insulin synthesis and secretion in rat insulinoma INS-1E cells." (PMID 38999937, 2024). "The presence of insulin or insulin receptor antibodies can distinguish insulin autoimmune hypoglycemia from insulinoma." (PMID 39125476, 2024). "Menin has been reported to suppress the expression and secretion of insulin in an insulinoma cell line." (PMID 38731926, 2024). "Among the patients diagnosed with insulinoma, baseline mean values of glycaemia were 48.0 ± 11.47 mg/dL (range 29–64), with insulin 7.45 ± 3.17 μU/mL and C-peptide 2.04 ± 0.69 ng/mL." (PMID 38451386, 2024). "The transfection of insulinoma cells with constitutively active Rab3a inhibited insulin release, indicating that continuous insulin secretion seems to demand the rapid cycling of Rab3a between an active and inactive state." (PMID 38999937, 2024). "This study investigated how exogenous nanomolar serotonin concentrations regulate insulin synthesis and secretion in rat insulinoma INS-1E cells with respect to vesicle trafficking-related proteins, Htr2b/Htr3a serotonin receptors, and ERK/Akt phosphorylation." (PMID 38999937, 2024). "To investigate how Rab26 regulates insulin secretion, we examined the subcellular location of Rab26 and the effects of its overexpression on the distribution of insulin granules in insulinoma cells." (PMID 37289842, 2023). "ASVS stimulates insulinoma to secrete insulin by selectively injecting calcium gluconate into the pancreatic artery to locate the tumor." (PMID 37455905, 2023). "Our study is the first to assess serum insulin concentration in dogs with insulinoma in relation to clinical staging." (PMID 37194422, 2023).